IL6 (interleukin 6)
Diseases named in the same sentence as IL6 in open-access papers (continued):
Sharing a sentence is not in itself a finding about the gene and the disease.
periodontal disease (continued). "The cytokines most implicated in periodontal disease include TNF-α, IL-1β, IL-6, IL-17A, INF-γ, IL-8, and, to a lesser extent, IL-12 and IL-18." (PMID 39062000, 2024). "Similar, IL-6 is a pro-inflammatory cytokine with a very well documented role in periodontal disease, having been demonstrated to actively participate in the initiation and the acute phase of the disease." (PMID 39682721, 2024). "Related to IL-6, several studies have focused on the potential role of this cytokine in directing the destructive processes in periodontal disease." (PMID 38791469, 2024). "IL6, through its downstream effects, has an influence on the deleterious nature of periodontal disease." (PMID 38826270, 2024). "Several cytokines have a recognized role in the pathogenesis of periodontal disease including interleukin-1(IL-1), interleukin-6 (IL-6), tumor necrosis factor- α (TNF- α) and vascular endothelial growth factor (VEGF)." (PMID 38671416, 2024). "These arguments are based on the fact that TNF-α, IL-1, and IL-6 are produced in large quantities in adipose tissue and as a result of periodontal disease." (PMID 39337292, 2024). "Periodontal disease, compared to the controls, triggered an increase in inflammatory cytokines (IL-6, TNF-α) in the uterus and oral cavity, which was abrogated by nisin treatment." (PMID 39203489, 2024). "Periodontal disease triggered higher levels of inflammatory cytokines (IL-6, TNF-α) in the uterus, which was abrogated by nisin treatment." (PMID 39203489, 2024). "Periodontal disease induces chronic inflammation, releasing pro-inflammatory cytokines like IL-6, TNF-α, and CRP, which exacerbate neuroinflammation, disrupt the blood–brain barrier, and promote neurodegeneration." (PMID 39768299, 2024). "The RT-qPCR results indicated a significant increase in the expression of key proinflammatory cytokines, such as IL-1β, TNF-α, and IL-6, in brain tissues as a result of Pg-induced periodontal disease." (PMID 38892314, 2024). "Measurements of the IL-6 levels in gingival crevicular fluid (GFC), as well as in serum, can be important diagnostic and prognostic factors in periodontal diseases (PD) and in assessing their impact on a range of related inflammatory diseases." (PMID 38396821, 2024). "Based on the available data, the levels of both IL-17 and IL-6 appear to be elevated in periodontal disease, suggesting a correlation between IL-17 and IL-6 in periodontal disease." (PMID 39215253, 2024). "Our results showed that TNFα and IL-6 production levels were significantly increased in patients with periodontal disease in comparison with HC." (PMID 36599866, 2023). "The increase in serum IL-6 due to periodontal disease reduced claudin-5 levels in the brain blood vessels, resulting in increased BBB permeability." (PMID 37440496, 2023). "The evidence suggests that circulating levels of IL-6 are implicated in poor clinical outcomes in DM1 and susceptibility to periodontal disease." (PMID 36769794, 2023). "PCOS was linked to increased levels of CRP, interleukin-6, and TNF- α, all of which contribute to chronic low-grade inflammation and raise the risk of periodontal disease." (PMID 38021744, 2023). "Among these secreted cytokines, especially tumor necrosis factor‐alpha (TNF‐α), interleukin (IL)‐1 (β and α), and IL‐6 are important for the development of periodontal disease." (PMID 37970391, 2023). "This scoping review highlights the immune-related similarities between the COVID-19 infection and periodontal disease, especially focusing on serum cytokine levels, such as IL-1β, IL-6, and TNF-α levels." (PMID 37106750, 2023). "Obese individuals have higher levels of IL-6 and TNF-α, which make them more susceptible to developing destructive periodontal disease." (PMID 37629193, 2023).
periodontal disease (continued). "Inflammatory mediators released from periodontal disease, such as interleukin-6, tumor necrosis factor-alpha, and prostaglandin E2, can escape through damaged periodontal tissue pockets and produce systemic effects elsewhere in the body." (PMID 37509588, 2023). "During the periodontal disease progression, circulating levels of pro-inflammatory cytokines increase, including interleukins (IL-1β, IL-2, IL-6, IL-8)." (PMID 37936877, 2023). "Th17 cells play a central role during the establishment of periodontal disease, and these cells regulate the expression of proinflammatory mediators, such as IL6, IL-17 and IL-23." (PMID 36011941, 2022). "IL-6 families play especially important roles in the pathogenesis of periodontal disease and many other inflammatory diseases and are correlated with clinical severity of periodontal diseases." (PMID 35047633, 2022). "Many pro-inflammatory cytokines, including IL‐1β, IL‐6, IL‐21, IL‐22, IL‐23, and IL‐17, take part in the pathogenesis of periodontal diseases." (PMID 35222410, 2022). "The GCF Interleukin-6 (IL-6) levels showed statistically significant decreases with probiotic supplementation compared to controls in patients with periodontal disease (SMD = 0.361, 95% CI: 0.079, 0.644, I2 < 0.001, p-value ≤ 0.05, and n = three studies)." (PMID 35268009, 2022). "A number of candidate gene studies showed that IL1A, IL1B, IL4, IL6, IL10, TNFA, FcγR, VDR, TLR2, TLR4, and MMP1 were the main genes associated with periodontal disease." (PMID 36294882, 2022). "Patients with periodontal disease had significantly higher levels of IL-1 and IL-6 in their saliva than those with healthy periodontium." (PMID 35368315, 2022). "Other inflammatory markers, such as interleukin-6, have been shown to be raised in periodontal disease, and interleukin-6 has been shown to be inversely linked with sensory recovery." (PMID 35208609, 2022). "According to some systematic reviews, our studied salivary molecules, IL-1β, IL-6, and MMP-8 are recognized as key salivary biomarkers with acceptable diagnostic reliability for periodontal disease." (PMID 35368315, 2022). "Given that the production of proinflammatory cytokines lies at the heart of periodontal diseases, we next utilized qRT–PCR and ELISA to examine the mRNA levels of TNFα, IL-6, and IL-1β in gingival tissues and related protein levels in mouse serum." (PMID 35588785, 2022). "We herein assessed the proportion of immunosuppressive cells and levels of IL-6 and immunosuppressive cytokines in the PB of patients with periodontal disease and/or cancer." (PMID 35804048, 2022). "Our analysis of the effects of probiotic supplementation on immunological outcomes indicated that the GCF levels of MMP-8 and IL-6 were reduced after probiotic supplementation in patients with periodontal disease." (PMID 35268009, 2022). "A pregnant woman with diagnosed periodontal disease had increased levels of IL-2, IL-4, IL-6, IL-10, TNF-α and INF-γ." (PMID 35055157, 2022). "There are mixed reports in the literature about the relationship between salivary IL-6 and dental and periodontal disorders." (PMID 35054284, 2022). "Similar inflammatory mediators, such as interleukin-6, tumor necrosis factor-alpha, and C-reactive protein, are increased in patients with severe periodontal disease." (PMID 36361416, 2022). "The proposed role of IL-6 in periodontal disease pathogenesis is through the stimulation of MMP production and the activation of pathways involved in inflammation." (PMID 35268009, 2022). "The level of IL-6 is related to the active stage of the disease, which is consistent with the detection results of gingival crevicular fluid in patients with periodontal disease." (PMID 35581339, 2022). "In previous studies, the production of pro-inflammatory mediators in the PDL was significantly inhibited by vitamin D in a periodontal disease model, including IL-6." (PMID 34362362, 2021).
periodontal disease (continued). "In the case of periodontal disease, several inflammatory molecules are released, such as IL-1β, IL-6, interleukin-8 (IL-8), LPS, TNF-α, and PGE2." (PMID 34833990, 2021). "Concentrations of four pro-inflammatory cytokines (IL-1β, IL-6, IL-8 and TNF-α) linked with periodontal disease were measured in the collected saliva of nine subjects in the probiotic gum group at each timepoint." (PMID 33962608, 2021). "In periodontal disease, the cytokines IL-1, TNFα und IL-6 activate osteoclasts via RANKL, resulting in increased resorption of the alveolar bone." (PMID 33771147, 2021). "Several studies have inferred that higher levels of IL-6 can have a significant impact on the diagnosis of dental caries and periodontal diseases." (PMID 33886621, 2021). "High levels of IL-1, TNF-α, and IL-6 have been also found in the gingival crevicular fluid and plasma of patients with periodontal disease." (PMID 34199256, 2021). "This study demonstrated that S. salivarius K12 and M18 were able to produce a proteinaceous small molecule capable of inhibiting IL-6 and IL-8 activation of primary human gingival fibroblasts by periodontal disease pathogens." (PMID 33962608, 2021). "The potential use of YKL-40 and IL-6 as biomarkers to diagnose periodontal disease was analysed through ROC curves." (PMID 32895666, 2020). "Tumour necrosis factor α (TNFα) and interleukin (IL)-6 represent proinflammatory cytokines that modulate the inflammatory response during periodontal disease." (PMID 32456146, 2020). "The usefulness of YKL-40 and IL-6 as biomarkers of periodontal disease was verified through the analysis of their sensitivity and specificity using ROC curves." (PMID 32895666, 2020). "Biomarkers showing high levels in periodontal disease were salivary IL-1β, IL-4, IL-6, MMP-8, and tissue inhibitor of matrix metalloproteinases (TIMP)-2, and those in the controls were tumor necrosis factor (TNF)-α, IL-10, IL-17, and IL-32." (PMID 33383828, 2020). "Studies have shown that with periodontal disease, there is an increase in inflammation markers, like IL-6 (Interleukin 6) and C-reactive protein (CRP) which were related to decreased physical capability and muscle strength in frail adults." (PMID 32858854, 2020). "The biomarkers showing elevated levels in the baseline saliva of patients with periodontal disease were IL-1β, IL-4, IL-6, MMP-8, and TIMP-2, while the control group showed high levels of TNF-a, IL-10, IL-17, and IL-32." (PMID 33383828, 2020). "IL-6 and IL-8, both inflammatory mediators, are known to be involved in the progression of periodontal disease." (PMID 33255259, 2020). "During periodontal disease, host inflammatory cells are recruited, and inflammatory cytokines, such as IL-1β, IL-6, and TNF-α, are released from fibroblasts, macrophages, connective tissue, and junctional epithelial cells." (PMID 33383828, 2020). "Particularly, many clinical studies have demonstrated the correlation between high TNF-α and IL-6 expressions and periodontal disease, highlighting their involvement and crucial role in the evolution of gingival inflammation." (PMID 33096800, 2020). "TNF, IL-6 and IL-17 have multiple overlapping functions that contribute to RA and periodontal disease by stimulating leukocyte activation and migration, chemokine expression and bone resorption." (PMID 31182740, 2019). "IL-6 contributes to the pathogenesis of periodontal diseases via inducing osteoclastogenesis, tissue destruction and bone resorption." (PMID 31531360, 2019). "In the course of periodontal disease, various proinflammatory mediators occur, such as interleukin- (IL-) 1, IL-6, and IL-8, IFN- γ, CCL5, TNF-α, prostaglandins, and metalloproteinases." (PMID 31355282, 2019). "Saliva, as a pooled sample, contains specific biomarkers for unique pathological aspects of periodontal disease, such as interleukin-1β (IL-1β), IL-6, IL-8, IL-11 and tumor necrosis factor-alpha (TNF-α)." (PMID 29740515, 2018).
periodontal disease (continued). "Interleukin-1 and interleukin-6 levels have been assessed as inflammatory markers in patients with periodontal disease." (PMID 29652898, 2018). "Patients with periodontal disease showed higher levels of cytokines (IL-2, IL-6, IL-10, and TNF-α) and PGE2." (PMID 30154640, 2018). "Plenty of evidence manifested that periodontal disease is linked with an increase of several markers of chronic inflammation, such as C-reactive protein (CRP), interleukin-6 and fibrinogen." (PMID 28814274, 2017). "The IL-6 SCP and NSCP groups exhibited similar age and smoking history, whereas the male population showed significantly higher prevalence of periodontal disease susceptibility compared to the female population (p=0.04)." (PMID 28624837, 2017). "IL-6 and IL-10 genes have both a significant effect on the initiation of periodontal disease and increased levels of these proteins have been found in the gingival crevicular fluid of sites with periodontal destruction." (PMID 28624837, 2017). "The patients with RA showed a greater tendency to develop periodontal disease than the controls, with lower salivary flow and higher levels of IL-6 in saliva." (PMID 28809379, 2017). "Periodontal disease mainly occurs as a result of the activation of host‐derived immune and inflammatory mechanisms induced by cytokines, including IL‐1β, IL‐6, and TNF‐α (2009; 1996)." (PMID 29744190, 2017). "Pro-inflammatory mediators, including Il-6, IL-1β and PGE2 are also associated with periodontal disease progression and alveolar bone resorption." (PMID 29075409, 2017). "Among the host mediators produced after microbial recognition, innate immunity cytokines such as TNF-α, IL-1, and IL-6 were the first to have their roles in periodontal disease pathogenesis unraveled." (PMID 28632755, 2017). "In our study, as in others, high levels of IL-6 were found in patients with periodontal disease as compared with healthy controls." (PMID 29075409, 2017). "Previous studies support a possible role of periodontal disease in the course of CVD by finding associations between periodontal parameters and IL-6 and TNF-α10,17,25." (PMID 27556206, 2016). "The levels of all inflammatory mediators in saliva and levels of all inflammatory mediators except IL-6 in serum significantly increased with severity of periodontal disease." (PMID 27978823, 2016). "IL-6 is the inflammatory cytokine produced after microbial recognition and is involved in the pathogenesis periodontal disease, such as osteoclast formation, bone resorption, and periodontal destruction." (PMID 27832188, 2016). "The levels of all inflammatory mediators in saliva and almost all inflammatory mediators except IL-6 in serum significantly increased with severity of periodontal disease." (PMID 27978823, 2016). "We found high levels of IL-6 in patients with periodontal disease when compared with healthy controls." (PMID 26644840, 2015). "Inflammatory cytokines such as IL-6 and IL-8 are believed to be the main pathological mediators in periodontal diseases." (PMID 25823008, 2015). "Compared with the gingival fibroblast tissue from healthy subjects, that from periodontal disease patients produced higher IL-1 before and after P. gingivalis challenge and pretreating gingival fibroblasts with IL-1α enhanced IL-6 production." (PMID 25884025, 2015). "IL-1β and IL-6 have been identified as the key inflammatory mediators in periodontal disease which lead to connective tissue degradation and alveolar bone resorption." (PMID 25806806, 2015). "Our study suggests that polymorphisms in the IL-4 gene not only affect the production of the IL-4 cytokine but can influence production of several other cytokines, such as IL-10, IFNγ, IL-1β, IL-6, and TNFα, which in turn can affect periodontal disease." (PMID 25530681, 2014). "In patients with periodontal disease, monocytes and dendritic cells within local periodontal tissues secrete various inflammatory mediators, including IL-1β, IL-6, and TNF-α." (PMID 23951003, 2013).
periodontal disease (continued). "Thus, if periodontal disease and these serum biomarkers share the same causal pathway, it was not surprising that severe periodontal disease was no longer significant in individuals in the highest two quartiles of serum IL-6 when being edentulous remained significant." (PMID 23950871, 2013). "With regard to periodontal diseases, an immunohistochemical study observed that a higher level of IL-6 was expressed in inflamed gingival tissues than in healthy control tissues." (PMID 24137277, 2013). "Serum biomarkers of inflammation including IL-6, CRP and sICAM-1 have been associated with periodontal disease and COPD morbidity." (PMID 23950871, 2013). "Periodontal disease being a chronic infection, shares pathogenic mechanisms of cardiovascular diseases with the release of some inflammatory mediators like PGE2, IL-1, IL-6, and TNF-α." (PMID 20407653, 2009). "Treating periodontal disease reduces pro-inflammatory mediator levels such as IL-6, tumor necrosis factor-α (TNF-α), CRP, and reactive oxygen species (ROS) and increases pro-resolving lipid mediators, which are anti-inflammatory in nature and help maintain homeostasis." (PMID 40916006, 2025). "Moreover, IL-6 plays a vital role in the progression of periodontal disease by promoting the formation of cells responsible for bone breakdown, which increases bone loss while decreasing bone growth." (PMID 41280712, 2025). "The same group of authors suggested that systemic and local IL-6 overproduction may play a vital role in the development of periodontal diseases." (PMID 40002575, 2025). "Additionally, inflammatory biomarkers such as IL-17, TNF-α, and IL-6 highlight direct links between local periodontal disease and systemic inflammation." (PMID 40076622, 2025). "Moreover, it was reported that IL-6 plays a key role in the pathogenesis of periodontal diseases by inducing the differentiation pf osteoclast and bone resorption." (PMID 40097880, 2025). "For example, a recent study demonstrated that elevated levels of IL-1β, IL-6, and MMP-8 are associated with increased periodontal disease severity among diabetic patients, suggesting a bidirectional relationship between glycemic control and periodontal inflammation." (PMID 40283677, 2025). "The first mechanism is supported by the presence of periodontal disease bacteria formed in atherosclerotic lesions in the coronary arteries and the second by the presence of increased levels of IL-1b, IL-6, IL-8 and TNF-a which are cytokines also related to ASCVD26." (PMID 41006734, 2025). "We propose that irisin may play a pivotal role in regulating the balance between adipokines such as visfatin and IL-6 within the context of periodontal disease." (PMID 41280712, 2025). "It has been associated with elevated secretion of pro-inflammatory cytokines such as interleukin-6 (IL-6), which may play a critical role in the pathogenesis and progression of periodontal disease." (PMID 41399637, 2025). "Veillonella, a genus linked to periodontal disease, showed a negative correlation with IP-10, IP-2, and IL-6." (PMID 40612273, 2025). "Interestingly, patients with periodontal disease have significantly higher levels of salivary IL-6, TRP, KYN, KYNA, picolinic acid (PA), and QA than periodontally healthy individuals (n = 40, p < 0.05)." (PMID 40559320, 2025). "The enrichment of IL-6 in classical inflammatory cascades and the involvement of irisin in energy-regulating pathways underscore the multifaceted pathophysiology of advanced periodontal disease." (PMID 41007333, 2025). "Also, polyphenols showed therapeutic effects on periodontal disease by inhibiting LPS-induced inflammatory cytokines (IL-1β, IL-6, IL-8) in PDL cells." (PMID 39548434, 2024). "The interactions of IL-6, IL-17, and IL-35 are hypothesized to potentially play roles in common pathways in the pathogenesis of periodontal disease." (PMID 39215253, 2024).